TNF (tumor necrosis factor)
Diseases named in the same sentence as TNF in open-access papers (continued):
Sharing a sentence is not in itself a finding about the gene and the disease.
Hyperammonemia (continued). "We repeated the analysis of TNF-a expression after 2 weeks of hyperammonemia." (PMID 32087723, 2020). "Additionally, in agreement with the increase in TNF-a, rats exposed to 2 weeks of hyperammonemia showed increased expression of p50 in microglia and astrocytes." (PMID 32087723, 2020). "We then assessed whether hyperammonemia can induce TNF-a expression in Purkinje neurons through the p50 and p65 subunits of NF-κB." (PMID 32087723, 2020). "We then analyzed the changes in TNF-a expression and NF-κB after 1 week of hyperammonemia." (PMID 32087723, 2020). "The induction of TNF-a by sustained hyperammonemia may contribute to the neurological alterations observed in hyperammonemia and hepatic encephalopathy by altering the function of Purkinje neurons and neurotransmission and by inducing neuronal death." (PMID 32087723, 2020). "This induction of TNF-a may contribute to the neurological alterations observed in hyperammonemia and hepatic encephalopathy by altering the function of Purkinje neurons and neurotransmission and by inducing neuronal death." (PMID 32087723, 2020). "TNF mediated liver damage may trigger hyperammonemia and thus further aggravate hepatic encephalopathy." (PMID 28801579, 2017). "However, the mechanism by which chronic hyperammonemia increases TNFα levels in cerebellum remained unknown." (PMID 38671534, 2024). "Hence, attenuation of inflammation, particularly mediated by TNFα, may reduce or prevent hyperammonemia." (PMID 28744340, 2017). "Hyperammonemia reduces the LC3 content in monocytes, and this effect is reversed by inhibiting PKA or blocking TNFα with anti-TNFα." (PMID 41601700, 2026). "Concerning neurons, the increased transcription of IL-1β in hyperammonemia and MHE is due to increased nuclear translocation of NF-κB, which promotes transcription of IL-1β, TNFα and other pro-inflammatory factors." (PMID 36593485, 2023). "Several studies confirmed that hyperammonemia activates the secretion of inflammatory cytokines (interleukin-6 (IL-6), interleukin-1beta (IL-1β), interferon gamma (IFN-γ), and tumor necrosis factor α (TNFα) in ammonia-induced astrocyte cultures." (PMID 35624703, 2022). "In rats with chronic hyperammonemia increased membrane expression of TNFR1 leads to increased nuclear translocation of NF-κB and, as a consequence, an increase of TNFα, IL1β, and glutaminase expression." (PMID 32917219, 2020). "It is noteworthy that the contents of the pro-inflammatory TNFα and of its receptor TNFR1 are increased 2-fold in EVs in hyperammonemia." (PMID 32121257, 2020). "Myostatin gene expression was also found to be affected by tumor necrosis factor -α (TNF-α), hormones (such as insulin-like growth factor (IGF-1), angiotensin II and thyroid hormones), nutritional supplementation, hyperammonemia, physical exercise and hypoxia." (PMID 32796600, 2020). "Hyperammonemia increases the EV release by monocytes and their content of TNFR1 and TNFα." (PMID 41601700, 2026). "Remarkably, R7050 strongly reduced TNFα expression in Purkinje neurons, microglia, and astrocytes, confirming that TNFα upregulation induced by hyperammonemia is mediated by TNFR1 activation and not by other TNF receptors, such as TNFR2." (PMID 41601700, 2026). "IL-17 levels and membrane expression of the IL-17 receptor are increased in cerebellum of rats with hyperammonemia and MHE, leading to increased activation of IL-17 receptor in microglia, which triggers activation of STAT3 and NF-kB, increasing IL-17 and TNFα levels, respectively." (PMID 38671534, 2024). "Despite this lack of an effect on TNF-a and NF-κB after 1 week of hyperammonemia, both microglia and astrocytes were activated in the cerebellum." (PMID 32087723, 2020). "This study shows that sustained (4 weeks), but not short-term (2 weeks), hyperammonemia induces the expression of TNF-a in Purkinje neurons in rats." (PMID 32087723, 2020).
Hyperammonemia (continued). "In agreement with its lack of an effect on TNF-a, we did not observe any effect of hyperammonemia on the subcellular distribution of p50 in Purkinje neurons, with the distribution remaining similar to that observed in control rats." (PMID 32087723, 2020). "We also show that after 1 week of hyperammonemia, both microglia and astrocytes are activated, but TNF-a expression is not yet induced." (PMID 32087723, 2020). "In conclusion the results of the present study show that LPS (with and without hyperammonemia), induces an increase in the plasma concentration of both TNF-α and 6-keto PGF1α, which correlate with a rise in both CBF and ICP." (PMID 25675251, 2015). "Hyperammonemia is also frequently complicated by systemic inflammation including increasing systemic and cerebral levels of vascular endothelial growth factor (VEGF), Tumor Necrosis Factor (TNF)-alpha and the interleukins (IL)-1beta and IL-6." (PMID 24433342, 2014). "We show here that IL-17 levels are also increased in cerebellum of rats with hyperammonemia and MHE, leading to increased activation of IL-17 receptor in microglia, which triggers activation of STAT3 and NF-kB, leading to increased levels of IL-17 and TNFα, respectively." (PMID 38671534, 2024). "Sustained (4 weeks) but not short-term hyperammonemia induces TNF-a in Purkinje neurons in rats." (PMID 32087723, 2020). "However, it remains unclear how hyperammonemia induces an increase in TNF-a in the cerebellum and which cell types show increased TNF-a content." (PMID 32087723, 2020). "As this is not a common situation, we assessed whether sustained hyperammonemia is necessary for this induction of TNF-a and whether such induction also occurs after shorter periods of hyperammonemia." (PMID 32087723, 2020). "Interestingly, the addition of ammonia, does not course any additional elevation in the TNF-α or 6-keto PGF1α plasma concentrations indicating that the effect of hyperammonemia is not mediated through an elevation of the prostanoids or TNF-α concentrations." (PMID 25675251, 2015). "In fact, the data reported here show that hyperammonemia induces the synthesis of TNF-a in activated microglia and astrocytes after 2 weeks of hyperammonemia, when TNF-a was not increased in Purkinje cells." (PMID 32087723, 2020).
male infertility (26 papers, 2015 to 2025). The inability of the male to effect fertilization of an ovum after a specified period of unprotected intercourse. "As such, male infertility has also been linked to inflammatory biomarkers such as IL-6 and TNF-α and -β by disrupting the penile endothelium though increasing ROS testicular tissue levels." (PMID 38885232, 2024). "There are different studies supporting the evidence of the association between TNFα gene polymorphisms, that cause an overexpression of TNFα, and male infertility risk." (PMID 38900205, 2024). "Given that the A allele leads to increased expression of TNFα, anti-TNFα agents could be a useful treatment for male infertility." (PMID 28670429, 2017). "The pro-inflammatory cytokine TNF-α inhibits LH function directly, leading to a reduction in testosterone production and contributing to male infertility." (PMID 40075794, 2025). "This disruption is caused by the secretion of inflammatory factors, such as IL-6, IL-1β, TNFα, and I IFNs, which disrupt sperm formation and transport, ultimately resulting in male infertility." (PMID 38300431, 2024). "Male infertility is well recognized to be brought on by the unchecked production of pro-inflammatory cytokines in the testes, such as IL-1b and TNF-a, which are damaging to spermatogenesis." (PMID 38500117, 2024). "Inflammation is one of factors leading to the male infertility through destruction of spermatogenesis; TNF-α has been reported to negatively impact spermatozoa motility." (PMID 34537068, 2021). "The aim of this study was to investigate the potential association between TGF-β3 (TGFB3) and TNF-α (TNF) gene polymorphisms and male infertility." (PMID 26612435, 2015). "Sleep deprivation could decrease sperm motility and cause male infertility by regulating the expression of Interleukin (IL6), nitric oxide synthase (INOS), and tumor necrosis factor alpha (TNFα)." (PMID 39413105, 2024). "This confirms that activation of the TNF-α/NF-kB signaling pathway may downregulate testosterone production in Leydig cells, leading to male infertility." (PMID 39457533, 2024). "Tumor necrosis factor-alpha receptor 1 (TNFR1) mediates TNF-α activity and polymorphism in TNFR1 could lead to gene dysfunction and male infertility." (PMID 29082371, 2017). "Therefore, the present study evaluated associations between polymorphisms of genes coding for TNF-α and TGF-β3, i.e. TNF and TGFB3, and male infertility." (PMID 26612435, 2015). "Our study did not reveal significant association between TNF rs1800629 polymorphism and male infertility in a Polish population." (PMID 26612435, 2015). "Furthermore, the KEGG pathway enrichment analysis showed that the common targets mainly regulated the disease of varicocele-associated male infertility through the HIF-1 signaling pathway, PI3K-Akt signaling pathway, Relaxin signaling pathway, and TNF signaling pathway." (PMID 37543801, 2023). "Moreover, active compounds from natural products in classical prescriptions have been shown to improve male infertility by modulating SASP markers, including IL-1β, IL-6, and TNF-α." (PMID 40552151, 2025). "Gossypol-induced male infertility markedly and significantly increased the levels of testicular TBARS, NO, TNF-α, ADAM-17, and interleukins (IL-1β, IL-6, and IL-18) while significantly decreasing the levels of both TIMP-3 and IL-12 compared with those of the control group." (PMID 29849861, 2018).
Oral leukoplakia (26 papers, 2012 to 2025). A thickened white patch on the oral mucosa that cannot be rubbed off. "In oral leukoplakia patients, salivary samples were studied, and the levels of salivary interleukin-6 and TNF-α were found to be significant as clinical diagnostic markers." (PMID 28397778, 2017). "IL-6 and TNF-α were associated to distinguish OSCC versus oral leukoplakia." (PMID 36412636, 2022). "Moreover, salivary IL-6 and TNF-α alterations may be implicated in the pathogenesis of oral Leukoplakia." (PMID 35888762, 2022). "In human saliva and serum, TNF-α, IL-8, and IL-6 exhibited an increasing trend among healthy individuals, oral leukoplakia patients, and OSCC patients (P < 0.05)." (PMID 41415031, 2025). "They reported higher concentrations of salivary TNF-α in OSCC compared to leukoplakia and healthy control volunteers." (PMID 40723410, 2025). "In the TNF signaling pathway, TNF-α expression transitions from minimal expression (normal) to co-expression by epithelial and inflammatory cells (leukoplakia) to strong expression by cancer cells themselves with dense inflammatory infiltration (cancer)." (PMID 41415031, 2025). "Salivary TNFα has been studied as a possible biomarker for leukoplakia; it has been shown that TNFα concentrations are elevated in the saliva of patients with dysplasia." (PMID 35888762, 2022). "Other research performed on patients diagnosed with oral leukoplakia showed that the levels of IL-6 and TNF in the saliva can be used as a proven significant clinical biomarker." (PMID 32899735, 2020). "The results of the present study demonstrated higher levels of salivary TNF-α in individuals with OSCC compared to leukoplakia and healthy control subjects with a high level of statistical significance." (PMID 31350970, 2019). "In view of the elevated levels of TNF – α in saliva of individuals with severe dysplasia, it can also be used to monitor the malignant transformation to leukoplakia to OSCC." (PMID 31350970, 2019). "Significant difference between salivary TNF - α levels of leukoplakia and controls with AUC was found to be 0.00 (p<0.001)." (PMID 31350970, 2019). "The present study was conducted to evaluate the role of salivary TNF- α in oral leukoplakia and OSCC using ELISA technique." (PMID 31350970, 2019). "There is also an increase in the salivary TNF-α levels with increase in the histological grade of differentiation in OSCC as well as leukoplakia." (PMID 31350970, 2019). "Salivary TNFα can be used for predicting Oral Leukoplakia and OralSquamous Cell Carcinoma (OSCC)." (PMID 36518124, 2022). "ROC curve analyses revealed that salivary TNF-α could serve as valuable biomarker for differentiating leukoplakia (oral epithelial dysplasia) from healthy controls with an area under the curve (AUC) of 0.968 (95% Confidence Interval: 0.930 – 1.000)." (PMID 31350970, 2019). "Since TNF-α is involved in all stages of carcinogenesis, including cellular transformation, it has been suggested as a marker (along with IL-12β) for monitoring malignant transformation in some oral potentially malignant disorders (OPMDs), such as oral leukoplakia." (PMID 39860614, 2025). "Moreover, analysis of inflammatory cytokines in the serum of leukoplakia rats revealed significantly elevated levels of TNF-α and IL-6, further supporting the hypothesis that microbial dysbiosis triggers inflammatory pathways that contribute to tissue damage and disease progression." (PMID 41199950, 2025). "IL-6, alongside tumor necrosis factor alpha (TNF-α), was found to discriminate between OSCC and oral leukoplakia." (PMID 34830096, 2021). "The descriptive statistics of levels of salivary TNF-α in three groups with OSCC group showing - median: 43.75; range: 16.5- 253, leukoplakia - median: 21.825; range: 7.8 – 91.5 and control group - median: 4.65; range: 2.15 – 21.6." (PMID 31350970, 2019).
Oral leukoplakia (continued). "The mean and standard deviation of the salivary levels of TNF-α in OSCC, leukoplakia and control groups are calculated and are 63.94 ± 56.05, 28.96 ± 20.94 and 5.75 ±3.98 respectively." (PMID 31350970, 2019). "Regarding the saliva, ELISA analysis levels of IL-6 (p = 0.0012), IL-8 (p = 0.0000), and TNF-α (p = 0.0492) were higher in patients with OSCC compared to healthy controls and patients with oral leukoplakia without associated dysplasia." (PMID 36980727, 2023). "Furthermore, there is also a place for detection of cytokines in saliva, for example IL-6 in oral leukoplakia or IL-1, IL-6, IL-8, VEGF, and TNF-α in tongue squamous cell carcinoma." (PMID 32670885, 2020). "Besides, Tumor Necrosis Factor alpha (TNF-α) and IL-8 levels were also found elevated in the leukoplakia samples." (PMID 31516665, 2019). "As the present study found that there is an increase in expression of salivary TNF- α levels from controls to leukoplakia to OSCC, this reinforces the hypothesis of TNF- α being a pro- tumorigenic." (PMID 31350970, 2019). "Interestingly, comparing leukoplakias with dysplasia to OSCC, significantly less TNF-α expression in the stroma (p = 0.0102) was found, which may support its role in progressive pre-malignancy." (PMID 36980727, 2023).
pancreatic ductal adenocarcinoma (26 papers, 2013 to 2025). An infiltrating adenocarcinoma that arises from the epithelial cells of the pancreas. "Pancreatic ductal adenocarcinoma develops within a dense desmoplastic stroma characterized by activated fibroblasts and tumor-associated macrophages that secrete pro-inflammatory cytokines such as interleukin-6 (IL-6) and tumor necrosis factor-α (TNF-α)." (PMID 41303856, 2025). "Induction of EMT in pancreatic ductal adenocarcinoma by tumor necrosis factor-α (TNF-α) and transforming growth factor-β (TGF-β) simultaneously reprograms glucose metabolism to enhance glycolysis." (PMID 32596154, 2020). "For example, upregulation may occur via tumour necrosis factor-α (TNF-α) through the nuclear factor kappa B (NF-κB) signalling pathway in pancreatic ductal carcinoma cells." (PMID 38541208, 2024). "Besides, a study in a pancreatic ductal carcinoma mouse model shows that TNF and TNFR1 are required for optimal cytotoxic CD8+ T function and tumor rejection." (PMID 37041130, 2023). "In particular, pancreatic ductal carcinoma cells exposed to the EMT-inducers Tumor Necrosis Factor α (TNFα) and TGFβ upregulate the expression of glucose transporters GLUT1 and GLUT 3 and the expression of several glycolytic enzymes (i.e., HK2, PKM2, LDH-A, and LDH-B)." (PMID 32932943, 2020). "A preclinical study combining oncolytic adenovirus Ad-mTNFα-mIL2 (expressing TNF-α and IL-2) with CAR-T cells targeting mesothelin showed significant tumor attenuation in pancreatic ductal adenocarcinoma models." (PMID 40539780, 2025). "Penny and colleagues also reported that pancreatic ductal adenocarcinoma produced TAMs expressing both M1 (IL‐1β, IL6, and TNF‐α) and M2 (CD163, CD206, and Arg1) markers." (PMID 37688511, 2023). "Indeed, Penny and colleagues also reported that pancreatic ductal adenocarcinoma-generated TAMs expressed both M1 (IL-1β, IL6, and TNF-α) and M2 (CD163, CD206 and Arg1) markers." (PMID 30927925, 2019). "This non-canonical pathway is the molecular basis for anti-CD40–induced repolarization of TAMs from a tumor-promoting M2 to a suppressive M1-like phenotype with upregulation of IL12, TNFα and INF-γ in KPC mice which spontaneously develop pancreatic ductal adenocarcinoma." (PMID 28467800, 2017). "Furthermore, freshly isolated TAMs from pancreatic ductal adenocarcinoma display M1 (HLA-DR, IL1B, TNFα) and M2 (CD163, IL10) characteristics." (PMID 28467800, 2017). "Thus, TNF and TNFR1 are required in pancreatic ductal carcinoma to ensure optimal CD8+ T cell-mediated immunosurveillance and tumor rejection." (PMID 24098720, 2013). "In a mouse model for pancreatic ductal adenocarcinoma, acquired resistance of tumor cells to immune checkpoint inhibition was shown to be mediated by decreased expression of IRF6, which results in an inability of tumor cells to be killed by TNF-α released from immune cells." (PMID 40569988, 2025). "Some chemokines, such as CCL5 (RANTES), CXCL10 and CCL2 induced by TNFα, also have been reported to locally recruit both CAR T cells and endogenous T cells when combined with adenoviral OV and mesothelin-redirected CAR T cells in pancreatic ductal adenocarcinoma model." (PMID 36353540, 2022).